MYCN (MYCN proto-oncogene, bHLH transcription factor)
Diseases named in the same sentence as MYCN in open-access papers (continued):
Sharing a sentence is not in itself a finding about the gene and the disease.
neuroblastoma (continued). "Our analysis suggested that MYCN non-amplified neuroblastomas were heterogeneous and could be classified into 3 subgroups based on their transcriptional profiling." (PMID 38553589, 2024). "Therefore, to characterize the influence of WDR5 and PDPK1 on mitotic gene expression in cells with high MYC levels, we performed a comparative transcriptomic analysis in neuroblastoma cell lines defined by MYCN-amplification, which results in high cellular levels of the N-MYC protein." (PMID 38605297, 2024). "Alternative examples of autoregulation have been found for the following master TFs: FOSL1 in HNCC, MYC in colorectal cancer, ASCL1 in small lung adenocarcinoma, ISL1 in ovarian cancer, FOXC1 in triple-negative breast cancer, and MYCN in MYCN-amplified neuroblastoma." (PMID 38542080, 2024). "Moreover, the frequency of MUC4 and MUC16 mutations in our study was considerably higher than that reported in a previous study on MYCN non-amplified neuroblastoma (70% vs. 26% for MUC4 and 38% vs. 14% for MUC16)." (PMID 39338204, 2024). "Classifying MYCN non-amplified neuroblastomas into high and low groups, we demonstrated that the AURKA mRNA levels alone could predict the overall survival (HR 4.8; P < 0.0001)." (PMID 38553589, 2024). "The nuclear receptor NR1D1 has been shown to correlate with MYCN amplification in NB patients and TFAP4 inhibition leads to differentiation of MYCN-amplified neuroblastoma cells, supporting the validity of the inferred target genes." (PMID 38702304, 2024). "To evaluate whether this observation is representative of what occurs in human tumors, we analyzed neuroblastomas with and without MYCN amplification." (PMID 38493213, 2024). "Moreover, high EZH2 or DOT1L expression had prognostic significance independent of MYCN amplification status, age of diagnosis and International Neuroblastoma Staging System (INSS) disease stage." (PMID 39501501, 2024). "If any one of these predictions demonstrated significant benefit, it would represent the first standard-of-care molecular biomarker selection for MYCN non-amplified neuroblastomas and a foundational step toward personalised therapy for this devastating disease." (PMID 38553589, 2024). "However, MTAP lesions have not been shown in neuroblastoma – in fact MTAP has been reported to be transactivated by MYCN." (PMID 39313128, 2024). "The pool of 66 samples was then processed for deconvolution of absolute immune signals and resulted in a sub-cohort of 45 samples composed of 20 MYCN-amplified and 25 non-MYCN-amplified neuroblastoma tumors that are characterized by similar-low enrichment from immune cells (≤10%)." (PMID 37835497, 2023). "Chromosome 11q deletion or MYCN amplification in neuroblastomas exhibit higher numbers of M2-polarized (CD163+) macrophages and an activated Th2-lymphocytes/M2-macrophage axis compared to neuroblastoma lacking these mutations." (PMID 38087370, 2023). "Similarly, a strong correlation between MYCN expression and ribosome biogenesis has been documented in neuroblastoma patients, with a negative impact on patient survival." (PMID 37175848, 2023). "Indeed, MYCN, ISL1, HAND2, and PHOX2B, together with GATA3 and TBX2, comprise the core regulatory circuit, an autoregulatory transcriptional loop that maintains the malignant phenotype of MYCN-positive neuroblastoma." (PMID 37297004, 2023). "However, the impact of GSK461364 on Myc is not yet well understood, as phenotypic effects from PLK1 inhibition, which are not dependent on MYCN amplification status, have been reported in neuroblastoma cell lines." (PMID 36902175, 2023). "Surprisingly, the famous neuroblastoma-related MYCN gene is not among the most frequent genes." (PMID 36870971, 2023).
neuroblastoma (continued). "Patient NB-006 had a neuroblastoma in which MYCN was not amplified in the sample assayed for CNA." (PMID 37189699, 2023). "Elucidating the function of ADAMTS9-AS2 in the LIN28B/let-7/MYCN axis and its role in suppressing proliferation, metastasis, and CSC properties and inducing neuroblastoma cell differentiation may open novel avenues for developing therapeutic approaches and pharmacological interventions." (PMID 37991019, 2023). "Abnormal MYCN expression is present at diagnosis and is never acquired during later tumorigenesis of MYCN-non-amplified neuroblastoma which might be the reason behind observation of metastasis in neuroblastoma patients at diagnosis." (PMID 37274289, 2023). "Five tumors were HGGs and one was a brain metastasis of an MYCN non-amplified neuroblastoma tumor." (PMID 37492101, 2023). "Therefore, this study aimed to assess the clinical significance and STMN1 function in neuroblastoma with and without MYCN amplification." (PMID 37760452, 2023). "As we have pointed out, MYCN-amplification augments mitochondrial function and OXPHOS in neuroblastoma tumours, therefore targeting Aurora-A might reverse this phenomenon and expose metabolic vulnerabilities previously deemed evasive due to the so-called undruggablity of MYCN." (PMID 37414143, 2023). "The SIOP Europe Neuroblastoma Group study demonstrated that boys with stage 1 disease without MYCN (v-myc myelocytomatosis viral related oncogene, neuroblastoma derived) gene amplification suffered more relapse episodes during the 5-year follow-up period than did female patients." (PMID 37479763, 2023). "John T. Powers (Dell Medical School at the University of Texas at Austin) gave an overview of the mechanisms of let-7 disruption in neuroblastoma and showed that multiple isoforms of let-7 agonist H19 long noncoding RNA (lncRNA) are highly expressed in MYCN non-amplified neuroblastoma." (PMID 37016725, 2023). "Furthermore, the prognostic significance of ZNF436 in neuroblastoma was independent of MYCN amplification and age of diagnosis." (PMID 37904225, 2023). "Interestingly, a recent report assessing 943 neuroblastoma patients demonstrated the ALK R1275Q mutation is the most frequent at relapse, occurring de novo in the absence of MYCN amplification." (PMID 37414143, 2023). "Furthermore, STMN1 knockdown inhibited neuroblastoma cell growth regardless of endogenous and exogenous MYCN overexpression." (PMID 37760452, 2023). "However, in primary neuroblastomas, RUNX3 acts as a tumor-suppressor, whereas RUNX1 bifunctionally regulates cell proliferation according to the characterized genetic and epigenetic backgrounds, including MYCN oncogenesis." (PMID 36831211, 2023). "Neuroblastoma with amplified MYCN expressed higher NCAPG than neuroblastoma without amplified MYCN." (PMID 37834394, 2023). "Most patients (n = 13, 76.5%) had INSS stage 4 neuroblastoma at diagnosis, including three patients <12 months of age, two of whom had MYCN amplification; the one without MYCN amplification was considered HR due to stage 4 refractory disease with progression in first-line therapy." (PMID 37629294, 2023). "STMN1 knockdown inhibited neuroblastoma cell growth regardless of MYCN overexpression." (PMID 37760452, 2023). "Additionally, the agent induced cell toxicity in MYCN-amplified neuroblastoma cells but not in unamplified cells." (PMID 38004392, 2023). "Therefore, MYC but not MYCN or CD47 expression in neuroblastoma cells appears to be a significant regulator of T cell function in the tumor microenvironment." (PMID 36768931, 2023). "The present study was undertaken to determine whether neuroblastoma cells lacking MYCN amplification include heterogeneous cellular phenotypes." (PMID 38095019, 2023).
neuroblastoma (continued). "Neuroblastoma (NB), retinoblastoma (RB), medulloblastoma (MB), Wilms tumor (WT), and rhabdomyosarcoma (RMS) are examples of embryonal tumors with MYCN dysregulation." (PMID 37046804, 2023). "Profiles of T-UCRs in representative neuroblastoma tumors and a signature of sevenT-UCRs (uc.347, uc.350, uc.279, uc.460, uc.379, uc.446, uc.364) were found highlyexpressed in highly aggressive MYCN-amplified tumors compared to MYCN-non-amplifiedsamples." (PMID 36622962, 2023). "Two children in this series with negative MYCN, no 1p deletion and after GTR survived, suggesting that surgical treatment of metastases might be favorable especially in cases of MYCN negative neuroblastoma." (PMID 37466795, 2023). "As L-MYC and MYCN (also referred to as N-MYC) are MYC family members, it prompted us to investigate whether DNA-PKcs inhibitor (henceforth, DNA-PKi) could inhibit the cell growth of MYCN-amplified neuroblastoma." (PMID 37240360, 2023). "This study was performed using MYCN-non-amplified neuroblastoma cell lines SH-SY5Y and SK-N-SH." (PMID 37274289, 2023). "Therefore, neuroblastomas are a negative control to exclude regulation of T cells in the tumor microenvironment by MYCN expression in malignant cells." (PMID 36768931, 2023). "At the same time, our data may as well indicate that the MYCN expression level is an essential clinical marker but might not be a necessary target for the treatment of neuroblastoma." (PMID 35805002, 2022). "Anti-PD-L1 monoclonal antibody therapy is clinically approved for several types of cancer, and may combine effectively with the PD-L1 upregulation on MYCN-non-amplified neuroblastoma cells resulting from PBNP-PTT treatment." (PMID 35326601, 2022). "In Stage 4 neuroblastoma patients without MYCN amplification, high TRPM2 expression correlated with worse patient event free survival compared to patients with low TRPM2 levels 40,42, suggesting that in this subgroup TRPM2 has an important role in modulating metastatic and/or refractory disease." (PMID 36446940, 2022). "As such, upregulation of PVR in MYCN-non-amplified SH-SY5Y neuroblastoma cells by PBNP-PTT-administered thermal doses may enable increased NK cell-mediated tumor clearance." (PMID 35326601, 2022). "Three different neuroblastoma cell lines of ADRN MYCN-amplified, ADRN MYCN non-amplified, and MES subtype cells were treated with all-trans-retinoic acid (ATRA) and the super-enhancer landscape after treatment and upon subsequent removal of retinoic acid was studied." (PMID 36147741, 2022). "However, overexpression of E2Fs fails to activate MYCN transcription in MYCN non-amplified neuroblastoma, indicating that E2Fs are necessary but not sufficient regulators of MYCN." (PMID 36479072, 2022). "In order to confirm this hypothesis, we firstly reanalyzed an RNA-SEQ dataset from 39 neuroblastoma cell lines using the same definition for MYCN-amplified and MYCN-nonamplified groups described in the study." (PMID 35805002, 2022). "The adrenergic identity of the ADRN subtype of neuroblastoma cells is maintained by a transcriptional core regulatory circuit (CRC) of predominantly developmental regulators of neurogenesis including PHOX2B, GATA3 and ASCL1, whose expression is further maintained by high levels of MYC or MYCN." (PMID 36263020, 2022). "Interestingly, several chemokines have been found at higher concentrations in the MYCN-nonamplified neuroblastoma microenvironment and can be secreted by neuroblastoma cells to selectively recruit specific immune cell subsets." (PMID 36923280, 2022). "Moreover, the prognostic significance of E2F1 or E2F3 in neuroblastoma was independent of MYCN amplification and age of diagnosis." (PMID 35764946, 2022). "Increased vulnerability due to high-level transcription from super-enhancers, which has also been proposed for MYCN-amplified versus non-amplified neuroblastoma cell lines, may be considered as an explanation for the increased neuroblast sensitivity." (PMID 35681734, 2022).
neuroblastoma (continued). "The nomogram model could predict the overall survival of paediatric neuroblastoma and MYCN nonamplified paediatric neuroblastoma with high specificity and sensitivity." (PMID 35655142, 2022). "When MYCN was knocked-down by RNAi in selected neuroblastoma cell lines, cyclin A1 (CCNA1, OMIM 604036) and cyclin G2 (CCNG2, OMIM 603203) were upregulated alongside the cyclin-dependent kinase inhibitor CDKN1C, suggesting a functional connection between MYCN amplification and cell cycle control." (PMID 35804856, 2022). "An aggressive form of neuroblastoma (NB), a malignant childhood cancer derived from granule neuron precursors and sympathoadrenal lineage, frequently comprises MYCN amplification/elevated N-Myc expression, which contributes to the development of neural crest-derived embryonal malignancy." (PMID 36290282, 2022). "Therefore, neuroblastoma with MYCN amplification display an impaired ability to recruit monocytes, MDC and PDC, in contrast to MYCN-nonamplified neuroblastoma." (PMID 36923280, 2022). "We observed that the migration of monocytes, myeloid and plasmacytoid DC induced by MYCN-nonamplified neuroblastoma supernatants was abrogated by the addition of anti-CCL2 antibodies, demonstrating the involvement of the CCR2/CCL2 axis in their recruitment by these tumors." (PMID 36923280, 2022). "To investigate whether MYCMI-7 affects growth of typical MYC-driven tumor cells, we utilized a panel of childhood neuroblastoma cells with or without MYCN-amplification as well as a set of Burkitt's lymphoma cell lines, which carry MYC translocations." (PMID 36874405, 2022). "Therefore, PHGDH expression is also important in neuroblastoma without MYCN amplification as a prognostic factor as well as a therapeutic target." (PMID 36319669, 2022). "Considering that GPX4 is an essential gene in many cancer cell lines, it will be important to assess whether GPX4 ablation also affects the growth of corresponding MYCN‐low neuroblastomas (and therefore whether GPX4 inactivation would selectively impair MYCN‐high tumour growth)." (PMID 35908258, 2022). "It has been shown that CCL2 expression is repressed in MYCN-amplified neuroblastoma cells, and our analysis using two different public transcriptomic datasets confirm that CCL2 transcription was lower in MYCN-amplified neuroblastoma (which may arise from tumor or immune cells)." (PMID 36923280, 2022). "Overall, our findings highlight a major role for CCL2/CCR2 axis in monocytes, myeloid and plasmacytoid cells recruitment toward MYCN-nonamplified neuroblastoma, allowing further immune cell recruitment, and show that these tumors present a microenvironment that can favor DC responses." (PMID 36923280, 2022). "MYCN amplification is not restricted to neuroblastoma, and restoration of RA treatment could be beneficial in different MNA-tumors." (PMID 35490242, 2022). "Moreover, E2F1 was a prognostic maker of neuroblastoma independent of MYCN amplification, age of diagnosis and E2F3 expression in TARGET, GSE85047 and E-MTAB-1781 datasets." (PMID 35764946, 2022). "Only 1 patient (with MYCN-non-amplified neuroblastoma) had disease progression." (PMID 36686814, 2022). "Patients had HRNB if they were at least 12 months of age with INSS stage 4 neuroblastoma (primary tumor with dissemination to the distant lymph nodes, bone, bone marrow, liver, skin and/or other organs, except as defined for 4S), or <12 months of age with INSS stage 4 disease and MYCN amplification." (PMID 35883927, 2022). "Compared to neuroblastomas, GNs do not show MYCN gene amplification." (PMID 36239827, 2022). "MYCN status inside NB limits current clinical application, but multiple studies have demonstrated that inhibition of fatty acid synthesis induces differentiation of neuroblastoma independent of MYCN status." (PMID 36114560, 2022).
neuroblastoma (continued). "We also observed a continuum of CCL2 expression with low CCL2 expression in some MYCN-nonamplified neuroblastoma, suggesting that other mechanisms could repress CCL2 transcription." (PMID 36923280, 2022). "Overall, our findings highlighted a major role for CCL2/CCR2 axis in monocytes, myeloid and plasmacytoid cells recruitment toward MYCN-nonamplified neuroblastoma, and suggest that the recruited myeloid DCs will further recruit T lymphocytes by means of CCL19 and CCL22." (PMID 36923280, 2022). "In the International Neuroblastoma Risk Group (INRG) classification system, 11q deletion was associated with poor prognosis, mainly in patients with L2 or MS tumours who were fewer than 18 months old and lacked MYCN amplification." (PMID 35137546, 2022). "However, drug resistance against ALK inhibitors and the absence of direct antagonists for MYCN limit the treatment of neuroblastoma in clinic." (PMID 36585695, 2022). "In this study, we describe metabolic rewiring in MYCN-amplified adrenergic neuroblastoma cells, where high consumption of cysteine used for the synthesis of cellular building blocks at the expense of GSH synthesis and ROS clearance creates a new MYCN-dependent liability." (PMID 35484422, 2022). "Prior to screening, we investigated ALK inhibitor responses of ALK-mutated neuroblastoma cell lines harboring MYCN amplifications (KellyALKF1174L, LAN-5ALKR1275Q) or non-amplified MYCN (SH-SY5YALKF1174L) to select a cell line and establish suitable ALKi concentrations for screening." (PMID 35689207, 2022). "Moreover, we tried to identify the differentially expressed genes in MYCN non-amplified younger neuroblastoma patients in TARGET dataset." (PMID 34116676, 2021). "Following the establishment of a murine neuroblastoma signature and a human neuroblastoma-specific transcriptional network, the algorithm “Virtual Inference of Protein activity by Enriched Regulon Analysis” (VIPER) was used to prioritize potential master regulators in MYCN-driven neuroblastoma." (PMID 34638267, 2021). "Moreover, human neuroblastoma samples showed a correlation between low levels of caspase-2 expression and increased patient survival in the subset of MYCN-non-amplified neuroblastomas." (PMID 34069817, 2021). "However, high ODC1 expression also predicts poor outcome in MYCN non-amplified neuroblastoma suggesting it has oncogenic abilities independent of MYCN." (PMID 33918978, 2021). "Thus, in the present review, we focus on the 11q loss mutation and discuss possible therapeutic strategies in unfavorable neuroblastoma without MYCN amplification." (PMID 34069817, 2021). "And MYCN non-amplified younger pediatric neuroblastoma patients had better prognosis." (PMID 34116676, 2021). "Importantly, neuroblastoma highly relies on fatty acid oxidation for energy production, and inhibition of β-oxidation leads to reduced growth of MYCN-amplified, but not of non-MYCN-amplified, cells and tumors." (PMID 33659885, 2021). "Furthermore, the authors could correctly identify MYCN and ALK amplification or diploid status in plasma samples from mice with established neuroblastoma xenografts and from patients at diagnosis, in accordance with FISH results on the primary tumor." (PMID 34680298, 2021). "Age related gene DST was an independent prognostic factor in MYCN non-amplified neuroblastoma." (PMID 34116676, 2021). "Notably, forced up-regulation of miRNA 17-5p-92 cluster in neuroblastoma cell lines that do not harbor MYCN amplification enhances their tumorigenic potential in animal models." (PMID 33718173, 2021). "However, compared with neuroblastoma patients without MYCN amplification, the mean age in MYCN amplified neuroblastoma patients was higher in GSE49710 dataset." (PMID 34116676, 2021).